AMH (anti-Mullerian hormone)
Diseases named in the same sentence as AMH in open-access papers (continued):
Sharing a sentence is not in itself a finding about the gene and the disease.
diabetes (10 papers, 2017 to 2026). "The model used for this group was logit(p) = −2.562 − 0.430 × AMH + 0.127 × BMI + 1.512 × hypertension + 0.956 × diabetes −1.145 × regular menstruation." (PMID 37958197, 2023). "The model used for this group was logit(p) = −3.778 − 0.823 × AMH + 0.176 × BMI + 2.660 × diabetes −1.527 × regular menstruation −1.117 × dysmenorrhea." (PMID 37958197, 2023). "During the follow-up Epidemiology of Diabetes Interventions and Complications (EDIC) study, coronary artery calcification (CAC) and serial measures of common cIMT were assessed, as well as AMH and serial measures of CVD risk factors." (PMID 30766706, 2017). "There were statistically significant differences (p < 0.05) between the control group and non-PCOS women with EPL in several basic characteristics (age, birth time, BMI, hypertension and diabetes, menstrual regularity, dysmenorrhea history) and blood test results (AMH, bE2, bP, CEA)." (PMID 37958197, 2023). "Reports in populations without diabetes have noted that AMH concentrations were not cross-sectionally associated with blood pressure or lipid profiles after adjustment for age and BMI." (PMID 30766706, 2017). "We have previously reported that type 1 diabetes is associated with lower AMH concentrations, and thus diabetes may have modified the relationship between AMH and CVD risk factor severity and between AMH and atherosclerosis." (PMID 30766706, 2017). "Studies of AMH and CVD risk factors in populations without diabetes conflict, although the associations between AMH and CVD risk factors, when documented, have been modest." (PMID 30766706, 2017). "Future investigations should replicate these findings between AMH, particular in larger populations without diabetes." (PMID 30766706, 2017). "Duration of diabetes, cigarette use, OCP use, BMI, waist circumference, DBP, and HDL did not vary significantly by AMH quartile." (PMID 30766706, 2017).
Hirsutism (10 papers, 2015 to 2026). Abnormally increased hair growth referring to a male pattern of body hair (androgenic hair). "BMI, severity of hirsutism, finding or severity of adult acne or female pattern hair loss, LH/FSH ratio, estradiol, AMH and insulin were similar in the two subgroups of PCOS women." (PMID 36291122, 2022). "Secondary outcomes include: the effect of the intervention on the PCOS phenotype, waist circumference, waist to hip ratio, ovulation rates, total testosterone, SHBG, free androgen index (FAI), AMH, hirsutism, acne, fasting glucose, blood pressure and all psychological parameters." (PMID 28264692, 2017). "Metabolic surgery contributed to marked improvement of abnormal menstruation, hirsutism, and levels of free testosterone, total testosterone, SHBG, and AMH in patients with PCOS." (PMID 35360056, 2022). "PCOS patients fulfilled all three Rotterdam Criteria, displaying oligo-/amenorrhoea (OA, p<0.0001), hirsutism (p = 0.003), and polycystic ovarian morphology (PCOM, p<0.0001) accompanied by elevated AMH levels (p = 0.0002)." (PMID 28045919, 2017). "There were statistically significant in irregular pattern of menstruation, AMH and FSH level, and presence of hirsutism between two groups." (PMID 26131012, 2015). "Other clinical (age, severity of hirsutism, finding or severity of adult acne or female pattern hair loss) and hormonal (LH/FSH ratio, estradiol, AMH) patterns were not different in patients with high or normal DHEAS of the same phenotype." (PMID 36291122, 2022).
hypothyroidism (10 papers, 2015 to 2025). Abnormally low levels of thyroid hormone. "Her past medical history included diagnostic laparoscopy for the evaluation of tubal patency, and Hashimoto thyroiditis with hypothyroidism and substitutional therapy in doses of 50 mcg daily, with AMH levels of 3.25 ng/mL." (PMID 36837508, 2023). "Diagnostic challenges occurred due to previous abortions, previous failure of IVF, history of hypothyroidism, AMH value of 0.252 ng/dL, and presence of adhesions." (PMID 36081974, 2022). "All things considered the possible decrease in the AMH levels in adult patients with TAI and/or hypothyroidism may have involved both thyroid hormone deficiency and autoantibodies." (PMID 34934402, 2022). "Few studies have evaluated AFC in women with TAI and/or hypothyroidism than in those with AMH." (PMID 34934402, 2022). "This is in line with some previous findings, but in contrast with data from a recent large cross-sectional analysis, in which neither ATD nor hypothyroidism were found to be associated with a poor ovarian reserve, as assessed by low age-specific AMH values." (PMID 26391773, 2015). "A possible reason behind this is that the age‐dependent decline in AMH disguises the influence of TAI and/or hypothyroidism on ovarian reserve." (PMID 34934402, 2022). "The average age was significantly higher (32.32 ± 5.04 vs. 35.33 ± 5.15 years; p = 0.04), and AMH level was significantly lower (3.57 ± 1.7 vs. 2.87 ± 3.17 ng/ml; p = 0.02) in patients with hypothyroidism but without AITD, as compared to the control group." (PMID 36477597, 2023). "This meta‐analysis aimed to investigate whether hypothyroidism and/or TAI affect the ovarian reserve and evaluated using the anti‐Mullerian hormone (AMH)." (PMID 34934402, 2022). "Results showed that despite the higher frequency of clinical hypothyroidism in the group with AMH < 1.1 ng/ml in both age groups, this difference was not statistically significant (P-value> 0.05)." (PMID 34598733, 2021).
ovarian carcinoma (10 papers, 2014 to 2024). A malignant neoplasm originating from the surface ovarian epithelium. "During this time, follicle stimulating hormone (FSH) levels remain elevated, whereas anti-Mullerian hormone (AMH) and inhibin B levels, as well as estrogen levels, decrease, and sex hormone levels are associated with breast, uterine and ovarian cancers." (PMID 37035104, 2023). "As AMH has been shown to inhibit tumor cell proliferation in several gynecological cancers, including ovarian cancer, through AMHR2‐mediated actions, the AMH‐AMHR2 signaling pathway has emerged as a promising therapeutic target for ovarian cancer." (PMID 39230026, 2024). "As this action occurs via a different mechanism to traditional chemotherapeutic agents, AMH has the capacity to inhibit proliferation of chemo-resistant ovarian cancer cells and cancer stem cells." (PMID 34557157, 2021). "In light of these grim statistics, human trials of AMH administration in women with advanced ovarian cancer would be appropriate, especially data suggests that AMH can be effective in inducing the regression of chemo-resistant tumour cells." (PMID 34557157, 2021). "Müllerian inhibiting substance, also called anti-Müllerian hormone (AMH), inhibits proliferation and induces apoptosis of AMH type II receptor-positive tumor cells, such as human ovarian cancers (OCs)." (PMID 29245952, 2017). "All these studies, based on physiological properties of AMH, have validated AMHRII as a target for treating ovarian cancers." (PMID 29245952, 2017). "Further studies should be performed for analyzing the decline of AMH with age progression in major pathologies, such as PCOS, unilateral ovariectomy, benign or malignant ovarian tumors and its predictive value the outcome of for ART technology." (PMID 25909458, 2015). "We found that there is not a significant value for the level of AMH between our ovarian cancer group and the non-ovarian cancer group (0.947)." (PMID 32185016, 2019). "The efficacy of controlling the development of mouse ovarian carcinoma (MOVCAR) cells was confirmed with recombinant human AMH, with no symptoms of toxicity during a 11-week treatment, equivalent to a continuous 7-year treatment in humans." (PMID 30884769, 2019).
female infertility (9 papers, 2010 to 2025). Diminished or absent ability of a female to achieve conception. "LH and progesterone level are rarely studied in correlation with AMH in female infertility, being hormonal factors implicated in ovulation and pregnancy outcome." (PMID 39336427, 2024). "The scoring system derived from the multivariable analysis assigns between 0 and 2 points for female age, AMH, female infertility diagnosis and TPMSC, respectively." (PMID 36069921, 2022). "Furthermore, the clinical scoring system includes factors such as female age, TPSC, female infertility etiology, and AMH levels." (PMID 40486001, 2025). "For what pertains female infertility, animal experiments have previously shown that pollution could affect the level of the anti-mullerian hormone (AMH), the hormone released by the cells of the ovaries which indicates their level of fertility." (PMID 33924000, 2021). "As serum AMH concentration is considered a biomarker which represents the dynamic reserve of developing ovarian follicles, a major clinical use of AMH measurement is to assess female infertility and to gauge the likely response to ovarian stimulation procedures for assisted reproduction." (PMID 32799874, 2020). "We observed no genome-wide genetic correlations between any category of female infertility and: (i) any reproductive hormone in this study, or (ii) thyroid stimulating hormone (TSH), or (iii) anti-Mullerian hormone (AMH), the latter two based on publicly available summary statistics (all P>0.05)." (PMID 38562841, 2024).
Hypertension (9 papers, 2019 to 2025). The presence of chronic increased pressure in the systemic arterial system. "The pathological features include a decrease in antral follicle count (AFC) and anti-Mullerian hormone (AMH) levels within six months postoperatively, which can also be evidenced by various menopausal symptoms, bone loss, and increased risk of hypertension." (PMID 41357576, 2025). "Patients with arterial hypertension had a slightly higher expression of AMH." (PMID 30884769, 2019). "There were noticeable differences in the level of AMH protein expression depending on the presence or absence of arterial hypertension." (PMID 30884769, 2019). "Based on the pooled logistic regression analysis, the effect of age-specific AMH quartiles on PE progression (adjusted for age, BMI, smoking status, and family history of hypertension) were not significant (OR1st vs 4th: 1.5, P-value: 0.1, CI: (0.9, 2.4))." (PMID 31752768, 2019). "Although hypertension was related to elevated AMH expression in EC cells (statistically not significant), neither type 2-diabetes, nor BMI correlated with AMH expression." (PMID 30884769, 2019). "According to the pooled logistic regression analysis, the effects of age-specific AMH quartiles on PE progression (adjusted for age, BMI, smoking status, and family history of hypertension) were not significant (OR1st vs 4th: 1.5, P-value: 0.1, CI: (0.9, 2.4))." (PMID 31752768, 2019). "In other words, if we were to replicate our analysis using individual-level health behavior and AMH non-adherence data, it is possible that health behavior would be an effect moderator given that health behaviors play a critical role in the etiology of high blood pressure control." (PMID 34886429, 2021).
hypogonadism (9 papers, 2012 to 2025). A disorder characterized by decreased function of the gonads. "As reported by others, adult males with FA had high rates of hypogonadism, and many had undergone HCT, either of which can be associated with low AMH levels." (PMID 39032500, 2024). "Low testosterone with normal or elevated AMH is characteristic of Leydig cell-specific hypogonadism." (PMID 24847309, 2014). "One of these patients, aged 16 years with hypogonadism, had undescended testes and an AMH level of 0 ng/mL; one was in remission 1 year after chemotherapy for acute myeloid leukemia (AMH of 3.2 ng/mL); and one was post-surgery and radiation therapy for HNSCC (AMH of 0.82 ng/mL)." (PMID 39032500, 2024). "Combined with the significant reduction of AMH and INHB in the female group, this further confirmed that the females had obvious hypogonadism." (PMID 37152325, 2023). "Although significant differences among the four groups were observed for LH and in men, for testosterone and AMH, we found FSH and INB basal levels to be the most useful criteria for characterizing the type of hypogonadism in our male and female PWS patients." (PMID 22559970, 2012). "Moreover, the present patient also experienced early menopause at 39 years old due to hypogonadism with FSH and LH levels in the postmenopausal range and low anti-Müllerian hormone (AMH) levels." (PMID 36438189, 2022).
ovarian tumors (9 papers, 2013 to 2023). "AMH emerged as a potential biomarker for several ovarian tumors in cows, mares, dogs, and cats." (PMID 31817280, 2019). "In 1992 AMH was identified as the marker of ovarian tumors of granulosa cell origin." (PMID 26977116, 2016). "Despite high levels of local AMH production, ovaries containing GCT respond to gonadotropin stimulation like the contralateral ovary with intra-ovarian tumor volume increasing during gonadotropin therapy." (PMID 30094759, 2018). "The localization of FOXL2, INHA, FOXO1, AMH, and DDX4 was detected in the granulosa cell or oocyte compartment of control ovaries, while ovarian tumor tissues from TGFBR1-CAG9Cre mice were immunoreactive with FOXL2, INHA, and FOXO1, supporting the development of GCTs in these mice." (PMID 29221447, 2017). "To define the molecular characteristics of ovarian tumors in TGFBR1-CAG9Cre mice, we performed immunostaining to examine the expression of a granulosa cell lineage marker FOXL2 and three other granulosa cell-expressed proteins, FOXO1, INHA, and AMH." (PMID 29221447, 2017).
thyroid autoimmunity (9 papers, 2015 to 2025). "Anti-Mullerian hormone (AMH) is one of the most reliable predictors of ovarian reserve but other factors including autoimmune thyroid diseases (ATD) have been associated with reduced fertility and poor COH outcome." (PMID 26391773, 2015). "Additionally, some conditions such as PCOS and thyroid autoimmunity have been associated with potential alterations in AMH levels, indicating a complex relationship between hormonal factors and fertility." (PMID 39336427, 2024). "However, the differences in AMH and oocyte count were also strongly associated with thyroid autoimmunity." (PMID 36477597, 2023). "A recent meta-analysis revealed significantly lower AMH in adult women with thyroid autoimmunity, compared to controls." (PMID 39274315, 2024). "In women with low serum AMH levels the probability of a successful outcome is low, independently from thyroid autoimmunity." (PMID 26391773, 2015). "Aim of the present study was to investigate the relationship between thyroid autoimmunity and ovarian reserve, as assessed by serum AMH concentrations, and to evaluate their respective role on the outcome of COH, being defined as ovarian response to recombinant gonadotropins." (PMID 26391773, 2015). "Our study aimed to investigate the influence of age, BMI, 25-OH vitamin D level, and thyroid autoimmunity on AMH in euthyroid non-PCOS women undergoing IVF." (PMID 39336427, 2024).
Turner syndrome (9 papers, 2012 to 2025). Turner syndrome is a chromosomal disorder associated with the complete or partial absence of an X chromosome. "Turner syndrome patients are prone to be at a higher risk of accelerated OR loss; monitoring of AMH in such cases seems to be an excellent indicator of premature ovarian insufficiency, suggesting timely interventions." (PMID 26977116, 2016). "Association between detectable AMH levels and spontaneous puberty in turner syndrome patients." (PMID 41030846, 2025). "AMH levels were consistently lower in Turner Syndrome (TS) patients compared to healthy controls, and detectable AMH remained a strong predictor of spontaneous puberty and reduced risk of premature ovarian insufficiency (POI)." (PMID 41030846, 2025). "These subgroup findings highlight the dual influence of biological variation (karyotype) and technical limitations (assay methodology) on AMH interpretation in Turner Syndrome." (PMID 41030846, 2025). "This systematic review synthesized evidence from nine studies evaluating serum Anti-Müllerian Hormone (AMH) as a biomarker of ovarian function and spontaneous puberty in Turner Syndrome (TS)." (PMID 41030846, 2025). "In conclusion, AMH appears to be a promising biomarker of ovarian reserve in Turner syndrome, with mosaic karyotypes deriving the greatest clinical benefit." (PMID 41030846, 2025). "This funnel plot visually assesses the risk of publication bias across the studies included in the systematic review comparing Anti-Müllerian Hormone (AMH) levels between Turner Syndrome patients and healthy controls." (PMID 41030846, 2025). "According to these PICO elements, the study’s leading review question was: In Turner syndrome patients, how does serum AMH level compare between those with normal ovarian function and spontaneous puberty versus those with impaired ovarian function or delayed or absent puberty?" (PMID 41030846, 2025). "Even though ESHRE (European Society of Human Reproduction and Embryology) classification of POI did not include AMH as a marker of ovarian reserve, several other studies demonstrated its role in predicting POI in healthy women and Turner’s syndrome patients." (PMID 29176793, 2017).
atherosclerosis (8 papers, 2013 to 2024). A disease characterized by the build-up of fatty material and calcium deposition in the arterial wall resulting in partial or complete occlusion of the arterial lumen. "Several epidemiological studies have explored the role of serum AMH as a marker of ovarian reserve and fertility in women but only a few studies have demonstrated its inverse association with atherosclerosis and cardiovascular disease." (PMID 31511566, 2019). "Higher serum AMH levels of female premenopausal cynomolgus macaques decrease the risk of Atherosclerosis and correlate negatively with plaque area." (PMID 30288163, 2017). "Among midlife women with type 1 diabetes, AMH has slight but significant associations with subclinical measures of atherosclerosis." (PMID 30766706, 2017). "In this regard, related animal studies on AMH association with atherosclerosis are available for rhesus monkeys." (PMID 28715487, 2017). "Whether AMH could subsequently increase risk of atherosclerosis via CVD risk factors or through an independent pathway has not been well-studied." (PMID 30766706, 2017). "Finally, we note that due to our sampling strategy of AMH measures prior to menopause, our power was limited to detect relationships between lower concentrations of AMH with greater burden of subclinical atherosclerosis or adverse risk factors." (PMID 30766706, 2017). "The importance of this is currently unknown, although it is consistent with recently observations linking AMH to atherosclerosis in rhesus monkeys and to the diameter of the abdominal aorta in health men." (PMID 23940675, 2013). "Thus, we were able to examine whether AMH was associated with CVD risk factor profile and measures of subclinical atherosclerosis among women with type 1 diabetes." (PMID 30766706, 2017). "It is notable that in our study of adolescent females, where confounding by characteristics such as smoking or an effect of existing undiagnosed atherosclerosis on AMH is highly unlikely, we did not observe an association even before multivariable adjustment for potential confounders." (PMID 23762215, 2013). "Levels of anti-Müllerian hormone (AMH), a marker that expresses ovarian reserve quantity, were furthermore negatively correlated with atherosclerosis development and plaque size in a prospective primate study." (PMID 27651793, 2016).